ENSG00000241962 (novel protein, C2orf15-MRPL30-novel lincRNA readthrough)
Gene: Protein-coding gene on chromosome 2 (99,141,485 to 99,322,741, forward strand). Ensembl gene ENSG00000241962.
Genetic constraint (gnomAD): Missense variants: 186 observed, 200.42 expected, observed/expected ratio (o/e) 0.93, 90% interval 0.82 to 1.05. Synonymous variants: 68 observed, 64.6 expected, observed/expected ratio (o/e) 1.05, 90% interval 0.87 to 1.29.